PRDX2 (peroxiredoxin 2)
Diseases named in the same sentence as PRDX2 in open-access papers (continued):
Sharing a sentence is not in itself a finding about the gene and the disease.
cervical cancer (11 papers, 2009 to 2025). A primary or metastatic malignant neoplasm involving the cervix. "Only a few proteomic studies have been conducted in cervical carcinoma, for which proteins such as annexin A2, tropomyosin 1 and 2, peroxiredoxin 2 and HSP 27 have been pointed out as potential diagnostic markers." (PMID 19367286, 2009). "The study explored the significant roles of PRDX I and II (PRDX1 and PRDX2) in the context of BLM treatment in SiHa cervical cancer cells." (PMID 38821929, 2024). "The results above indicate that the expression levels of PRDX1 and PRDX2 are significantly elevated in both cervical cancer patients and cervical cancer tissues compared to normal levels." (PMID 38821929, 2024). "The analysis revealed that, compared to normal tissues, PRDX1 and PRDX2 expression levels were significantly higher in cervical cancer tissues." (PMID 38821929, 2024). "Further investigation into the impact of PRDX1 and PRDX2 on the prognosis and survival of cervical cancer patients was conducted, including their expression levels at various stages of the disease." (PMID 38821929, 2024). "Consistent with the previous findings, levels of PRDX1 and PRDX2 were significantly higher in cervical cancer tissues in comparison to normal cervical tissues." (PMID 38821929, 2024). "The research demonstrates that PRDX1 and PRDX2 modulate apoptosis in cervical cancer cells through the PI3K/AKT pathway-mediated ER stress, facilitated by the clearance of ROS." (PMID 38821929, 2024). "This part of the study aimed to further elucidate the roles of PRDX1 and PRDX2 in cervical cancer treatment." (PMID 38821929, 2024). "The research results emphasize the pivotal roles of PRDX1 and PRDX2 in the treatment of cervical cancer using BLM." (PMID 38821929, 2024). "PRDX2 is secreted by various cancer cells, including cells of cervical cancer, erythroleukemia, lung adenocarcinoma as well as macrophages and embryonic kidney cells." (PMID 36604669, 2023). "Immunohistochemical and immunoblot analysis of cervical cancer sections revealed overexpression of peroxiredoxin-2 in the cancer samples when compared to controls." (PMID 28261610, 2017). "Other studies have shown the strong expression of PRDX2 and 3 isoforms in cervical intraepithelial neoplasia and cervical cancer." (PMID 26061816, 2015). "In accordance with our findings, upregulation of TSAs (peroxiredoxin 2) has been detected in HPV16 E7-expressing cervical carcinoma cells." (PMID 19367286, 2009). "This suggests that modulating PRDX1 and PRDX2 expression could enhance BLM’s efficacy against cervical cancer." (PMID 38821929, 2024). "Moreover, the expression levels of PRDX1 and PRDX2 were consistently higher across different stages of cervical cancer." (PMID 38821929, 2024). "Additionally, the expression of thioredoxin 1, peroxiredoxin 1 and peroxiredoxin 2 was significantly up-regulated in post-chemotherapy tissues compared to pre-chemotherapy cervical cancer tissues." (PMID 31470801, 2019). "PRDX2 levels are increased in cervical cancer, colon cancer and metatstaic breast cancer in lung." (PMID 26061816, 2015). "Three proteins were uniquely altered in vaginal carcinoma (DDX48, erbB3-binding protein and biliverdin reductase) and five in cervical carcinoma (peroxiredoxin 2, annexin A2, sarcomeric tropomyosin kappa, human ribonuclease inhibitor and prolyl-4-hydrolase beta)." (PMID 19367286, 2009). "However, three proteins were significantly altered in vaginal cancer exclusively (DEAD box, erbB3-binding protein and biliverdin reductase), and six proteins in cervical cancer (peroxiredoxin 2, annexin A2, sarcomeric tropomyosin kappa, Rnas inhib chain A and prolyl-4-hydrolase beta)." (PMID 19367286, 2009). "SiHa cervical cancer cell lines were engineered with empty vectors, and specific knockdowns for PRDX1 and PRDX2 were created." (PMID 38821929, 2024).
cervical cancer (continued). "This suggests that targeting PRDX1 and PRDX2, possibly through the use of inhibitors, might amplify the anti-cancer efficacy of BLM in cervical cancer therapy." (PMID 38821929, 2024). "This strategy could potentially provide a more effective approach to combat cervical cancer, emphasizing the significant therapeutic potential of PRDX1 and PRDX2 modulation in conjunction with BLM treatment." (PMID 38821929, 2024). "In our study, PRDX2 is proposed as a nonclassically secreted protein in the context of cervical cancer, whereas previously it was reported as cytoplasmic." (PMID 28261610, 2017).
hepatocellular carcinoma (11 papers, 2016 to 2025). A malignant tumor that arises from hepatocytes. "For instance, PRDX2 enhances the proliferation and tumorigenicity of hepatoma cells by regulating the ERK/FoxM1/cyclin D1 signal axis." (PMID 34384442, 2021). "Similarly, PRDX2 attenuating the proliferation and migration was observed in hepatocellular carcinoma cells." (PMID 33791345, 2021). "Prdx2 depletion attenuated stemness of CSCs in hepatocellular carcinoma." (PMID 27894099, 2016). "However, PRDX2 is considered to perform an inconsistent function in hepatocellular carcinoma (HCC)." (PMID 32337219, 2020). "It has also been reported that PRDX2 is significantly downregulated in hepatocellular carcinoma (HCC) tissues in terms of both mRNA and protein expression, and that its low expression is suggestive of poor prognosis for HCC patients." (PMID 39234629, 2024). "Moreover, PRDX2 knockdown augmented H2O2-induced cell death in hepatocellular carcinoma SMMC-7721 cells through enhancing ROS generation in response to H2O2, whereas PRDX2 over-expression exhibited opposite effects." (PMID 28125800, 2017).
osteosarcoma (9 papers, 2016 to 2024). A usually aggressive malignant bone-forming mesenchymal neoplasm, predominantly affecting adolescents and young adults. "The observed association of PRDX2 in those with a poor response was subsequently confirmed by western blot in an independent cohort of 4 further osteosarcoma cases." (PMID 31722230, 2020). "Collectively, these two studies present PRDX2 expression as a candidate predictive biomarker for patient stratification to chemotherapy and may represent a causative driver of more aggressive disease in osteosarcoma." (PMID 31722230, 2020). "In osteosarcoma, expression of peroxiredoxin 2 (PRDX2) and 78 kDa glucose-related protein (GRP78) have been reported to be associated with poor treatment response." (PMID 37197427, 2023). "PRDX2 silencing resulted in increased sensitivity of osteosarcoma cells to chemotherapy (methotrexate, doxorubicin and cisplatin) and a decrease in cell proliferation, invasion and migration in functional assays." (PMID 37197427, 2023). "Although the number of differentially identified proteins is different, they found that peroxiredoxin 2 (PRDX2) is increased in osteosarcoma patients who poorly respond to chemotherapy compared to good responders." (PMID 36077137, 2022). "The expression of PRDX2 was higher in osteosarcoma patients that were poor responders to induction chemotherapy." (PMID 28432271, 2017). "In addition, PRDX2 depletion contributed to increased sensitivity to chemotherapeutic drugs in osteosarcoma cells." (PMID 28432271, 2017). "As an example, mass spectrometry was used to analyze protein expression in osteosarcoma biopsy samples and showed that patients whose biopsies contained higher expression of peroxiredoxin-2 (PRDX2) were less likely to respond to initial chemotherapy treatments." (PMID 29225558, 2017). "In addition, a recent study identified that PRDX2 is a predictive indicator for the induction chemotherapy response in osteosarcoma using proteomics study of open biopsy samples." (PMID 28125800, 2017). "Previously, we investigated the proteomic profiles of open biopsy samples obtained from osteosarcoma patients before chemotherapy and identified peroxiredoxin 2 (PRDX2) as a novel predictive biomarker with response to induction chemotherapy with ifosfamide, doxorubicin, and cisplatin." (PMID 27990096, 2016).
non-small cell lung carcinoma (8 papers, 2017 to 2023). A group of at least three distinct histological types of lung cancer, including non-small cell squamous cell carcinoma, adenocarcinoma, and large cell carcinoma. "We also measured PRDX2 expression of non-small cell lung cancer (NSCLC) cells and examined its roles in the proliferation and migration in vitro and in vivo." (PMID 32908916, 2020). "PRDX2 plays important roles in the development of tumorigenesis and tumor progression of non-small cell lung cancer." (PMID 32908916, 2020). "PRDX2, an important member of the peroxiredoxin family which acts as enzymatic antioxidant proteins, has been found to be upregulated in several cancer types, including gastric, colorectal, and non-small cell lung cancer (NSCLC) 19, 37-41." (PMID 35813474, 2022). "However, the biological role of PRDX2 in the progression of non-small cell lung cancer (NSCLC) is poor reported." (PMID 32337219, 2020). "Collectively, Prdx2 may be regarded as a potential target for clinical treatment of non-small cell lung cancer." (PMID 30988280, 2019). "For example, in non-small cell lung carcinoma (NSCLC) cells, S-nitrosylation of the antioxidant enzyme peroxiredoxin-2 (PRDX2) inhibits its enzymatic activity, resulting in H2O2 accumulation." (PMID 33925645, 2021). "In the non-small cell lung cancer model the following 5 DEPs were found to be involved in the GSH metabolism pathway (G6PD, PRDX2, IDH1, MGST1 and 6PGD), 4 DEPs in the PPP pathway (G6PD, TALDO1, TKT and 6PGD) and 1 DEP involved in the glycolysis pathway (ALDH3A1)." (PMID 28303926, 2017).
ovarian carcinoma (7 papers, 2017 to 2025). A malignant neoplasm originating from the surface ovarian epithelium. "High expression of PRDX2 is significantly associated with ovarian cancer progression including pathological grades II and III, and clinical stages III and IV, as well as with chemotherapeutic drug resistance." (PMID 33332365, 2020). "Urinary catalase, α-1 Acid Glycoprotein and Peroxiredoxin-2 can be useful biomarkers for early detection and treatment response of ovarian cancer." (PMID 33137912, 2020). "In conclusion, urinary micro-peptides [Catalase, α-1 Acid Glycoprotein and Peroxiredoxin-2] can be useful biomarkers for early detection and treatment response monitoring of ovarian cancer." (PMID 33137912, 2020). "In the present study, we found that elevated PRDX2 expression was correlated with a better PFS in all ovarian cancer patients, especially in serous ovarian cancer patients." (PMID 30104402, 2018). "Using the same antibody, there were 2 cases of high, 4 cases of medium, and 4 cases of low PRDX2 staining among the examined 11 ovarian cancer tissues." (PMID 30104402, 2018). "High PRDX2 expression was not linked to OS among all ovarian cancer patients treated with Platin, Taxol, and Taxol+Platin chemotherapy, but results among these three chemotherapeutic agents showed a better PFS in all ovarian cancer patients." (PMID 30104402, 2018). "However, elevated mRNA expression of PRDX2 was significantly correlated with better PFS for all ovarian cancer patients and serous ovarian cancer patients." (PMID 30104402, 2018). "However, few studies have focused on the relationship between PRDX2 expression and disease outcome in ovarian cancer patients." (PMID 30104402, 2018). "In addition, high expression of PRDX2 mRNA was correlated with a better PFS in grade II or III ovarian cancer patients." (PMID 30104402, 2018). "However, observation from HPA database revealed that PRDX2 protein expression was up-regulated in ovarian cancer tissues, suggesting that PRDX2 may promote the progression of ovarian cancer." (PMID 30104402, 2018). "Further studies need to be done to validate the prognostic values of PRDX2 and PRDX4 in ovarian cancer." (PMID 30104402, 2018). "However, the prognostic value of PRDX1, PRDX2, and PRDX4 in ovarian cancer requires further exploration." (PMID 30104402, 2018). "In contrast, we found that PRDX2 and PRDX4 showed better PFS in all ovarian cancer patients treated with Platin, Taxol, and Taxol+Platin chemotherapy, implying that PRDX2 and PRDX4 predict better prognosis in ovarian cancer patients treated with these three chemotherapeutic drugs." (PMID 30104402, 2018). "However, the use of PRDX1, PRDX2, and PRDX4 as a prognostic indicator in ovarian cancer needs further study." (PMID 30104402, 2018). "Furthermore, increased expression of PRDX2 in stages III and IV ovarian cancer patients was related to a better PFS." (PMID 30104402, 2018). "However, there is no further study on the prognostic value of PRDX2 in ovarian cancer." (PMID 30104402, 2018).
cardiac hypertrophy (6 papers, 2017 to 2025). "The downregulation of Prdx2 has been implicated in isoproterenol‐induced cardiac hypertrophy." (PMID 39763059, 2025). "In an acute myocardial infarction model, PRDX2 was shown to enhance cardiomyocyte inflammation and myocardial hypertrophy." (PMID 39338362, 2024). "Together, our data show that STVNa confers protection against Iso-induced myocardial hypertrophy primarily through the Prdx2/ROS/Trx1 signaling pathway." (PMID 31968660, 2020). "Considering the important role of Prdx2 and Trx1 in hypertrophied heart, therapies aimed at inhibiting Prdx2 and Trx1 are likely to be effective for the prevention of cardiac hypertrophy." (PMID 31968660, 2020). "Taken together, our results indicate that PRDX2 promotes cell survival but is also involved in inflammatory myocardial hypertrophy in acute infarcted." (PMID 28765537, 2017). "Overall, these results indicate that PRDX2 promotes angiogenesis and myocardial hypertrophy but this is mediated by TLR4." (PMID 28765537, 2017). "Taken together, our results indicate that PRDX2 plays two roles: it increases cell survival in hypoxia on the one hand but contributes to inflammatory myocardial hypertrophy in acute infarcted on the other." (PMID 28765537, 2017). "Immunocytochemistry and immunofluorescence analysis show that overexpression of PRDX2 promotes angiogenesis and myocardial hypertrophy." (PMID 28765537, 2017). "By immunocytochemistry and immunofluorescence, we have shown that overexpression of PRDX2 promotes angiogenesis and myocardial hypertrophy." (PMID 28765537, 2017). "PRDX2 decressed expression during cardiac hypertrophy and may be a potential therapeutic target for the treatment of cardiac hypertrophy." (PMID 40646297, 2025). "It is also known that Prdx2 downregulates Iso-induced cardiac hypertrophy." (PMID 31968660, 2020). "Thus, we reasoned that STVNa treatment prevented cardiac hypertrophy by downregulating Prdx2 and Trx1 expression." (PMID 31968660, 2020). "In addition, immunocytochemistry and immunofluorescence analysis showed that overexpression of PRDX2 promotes angiogenesis and myocardial hypertrophy." (PMID 28765537, 2017). "We also assessed PRDX2 participation in angiogenesis and myocardial hypertrophy and whether it may be mediated by TLR4." (PMID 28765537, 2017). "PRDX2 overexpression in H9c2 cells also increases HUVEC migration, vasculogenic mimicry formation and myocardial hypertrophy related protein expression." (PMID 28765537, 2017). "The exact roles of Prdx2 and Trx1 during cardiac hypertrophy are not completely known." (PMID 31968660, 2020).
Parkinson disease (6 papers, 2013 to 2023). A progressive degenerative disorder of the central nervous system characterized by loss of dopamine producing neurons in the substantia nigra and the presence of Lewy bodies in the substantia nigra and locus coeruleus. "While Cdk-dependent phosphorylation of Prdx has been more comprehensively detailed for Prdx1, evidence of Prdx2 targeting by Cdk5/p35 and Cdk5/p25 complexes was described to reduce peroxidase activity and cause neuronal death in a toxin-induced model of Parkinson’s disease." (PMID 30678096, 2019). "The previous study discovered that Prdx-2 expression in the plasma is significantly lower in Parkinson’s disease patients." (PMID 36808393, 2023). "The aim of this study was to demonstrate that Prdx-2 has antioxidative and cytoprotective effects in the cell model of Parkinson’s." (PMID 36808393, 2023).
prostate carcinoma (6 papers, 2017 to 2025). A carcinoma that arises from epithelial cells of the prostate gland. "It has also shown that Prdx‐2 quenching causes the growth of prostate cancer cells, and blocks the cell cycle at G1 stage." (PMID 32232956, 2020). "Moreover, PRDX2 has been shown to promote the progression of prostate cancer by activating the androgen receptor (AR) signaling pathway." (PMID 40281661, 2025). "Moreover, the destruction of Prdx‐2 has also decreased the cell growth in Costa Rican resistant prostate cancer cells." (PMID 32232956, 2020). "Planning purposeful treatment of Prdx‐2 may be a new strategy to develop prostate cancer treatment." (PMID 32232956, 2020).
bladder cancer (5 papers, 2018 to 2023). "PRDX1 and 2 both act as diagnostic markers, but it is PRDX2 which is significantly increased in recurrence and can be used as a urinary surveillance marker in bladder cancer patients." (PMID 35812179, 2022). "Therefore, in the present study, the expression levels of PRDX 1 and PRDX2 were evaluated in bladder cancer tissue and patients' urine, and their association with recurrence on follow-up was evaluated." (PMID 35812179, 2022). "The most interesting protein upregulated in the samples of bladder cancer patients was peroxiredoxin 2 (PRDX2)." (PMID 37371512, 2023). "Urinary PRDX2 concentration was similarly found to be significantly more in bladder cancer patients compared to urine from healthy controls (p<0.001)." (PMID 35812179, 2022). "A significant elevation of urinary PRDX1 and PRDX2 concentration was found in bladder cancer patients and recurrent cases compared to the urine of healthy controls and primary bladder cancer patients (p<0.001 & p<0.01) respectively." (PMID 35812179, 2022). "Also, a comparative urine proteomics study reported the evaluation of PRDX2 in the urine sample of bladder cancer patients in different stages which confirms our study." (PMID 37501157, 2023). "Peroxiredoxin 2 (PRDX2) was upregulated in the samples of the bladder cancer patients." (PMID 37371512, 2023). "Unlike PRDX1, significant elevation of urinary PRDX2 was found in recurrent bladder cancer patients compared to primary bladder cancer patients (p=0.003)." (PMID 35812179, 2022).
lymph node metastasis (5 papers, 2017 to 2025). "In all stages of lymph node metastasis, the mRNA expression of PRDX2, PRDX4, and PRDX6 was higher in LUAD samples than in normal samples." (PMID 40303499, 2025). "In our previous study, all six PRDXs isoforms have been examined in paired cancer and non-cancer tissues by Immunohistochemistry and Western blotting, and the results showed that stage III patients and those cases with lymph node metastasis has a higher expression of PRDX2." (PMID 28125800, 2017). "Moreover, our results showed that over-expression of PRDX2 was significantly related with local invasion, TNM stage of CRC, tumor differentiation, and lymph node metastasis." (PMID 28125800, 2017).